FFAR3 (free fatty acid receptor 3)
Diseases named in the same sentence as FFAR3 in open-access papers (continued):
Sharing a sentence is not in itself a finding about the gene and the disease.
Sepsis (4 papers, 2015 to 2024). Sepsis is defined as life-threatening organ dysfunction caused by a dysregulated host response to infection. "To investigate the involvement of these receptors in the protective effects of SCFAs against sepsis-associated arrhythmia, we measured the levels of FFAR2 and FFAR3 using western blot." (PMID 39228788, 2024). "From a mechanistic perspective, the therapeutic effect of SCFAs in treating arrhythmias caused by sepsis is attributed to their antibacterial effect against C. sakazakii, but the involvement of SCFAs-related receptors, such as FFAR2 and FFAR3, also plays an important role." (PMID 39228788, 2024). "The identified FAM89A, FFAR3, G0S2, and FGF13 genes may help elucidate the molecular mechanisms underlying sepsis and drive the introduction of new biomarkers to advance diagnosis and treatment." (PMID 38050254, 2023). "Therefore, it appears likely that FFAR3, G0S2, and FGF13 participate in inflammation and metabolic reprogramming during sepsis." (PMID 38050254, 2023).
Alzheimer disease (3 papers, 2022 to 2025). A progressive, neurodegenerative disease characterized by loss of function and death of nerve cells in several areas of the brain leading to loss of cognitive function such as memory and language. "We aimed, first, to investigate the expression of the receptor in the hippocampus of Alzheimer disease (AD) patients at different stages of the disease and, second, to assess whether genetic inactivation of the Ffar3 gene could affect the phenotypic features of the APPswe mouse model." (PMID 35408893, 2022).
Cognitive impairment (3 papers, 2022 to 2025). Abnormal cognition is characterized by deficits in thinking, reasoning, or remembering. "Additionally, the same study demonstrated that the loss of FFAR3 is sufficient to reverse the cognitive impairment and amyloid-β (Aβ) pathology exhibited by the Tg2576 AD mouse model, which overexpresses the amyloid precursor protein (APP) carrying the Swedish mutation." (PMID 36362376, 2022). "In this study, we validated that TRF ameliorated AD‐induced cognitive impairments through PA‐FFAR3 pathway using a FFAR3 AAV." (PMID 40236783, 2025). "A recent study has already demonstrated that genetic inactivation of FFAR3 reverses the cognitive impairment showed by Tg2576 mice." (PMID 36362376, 2022). "In that study, mice were tested at an age corresponding to the onset of cognitive impairment manifestations, i.e., 12 months of age, suggesting that FFAR3 ablation could prevent the disease onset." (PMID 36362376, 2022). "The combination of SCFAs and FFAR3 suppressed ERK/JNK/NF‐κB signaling, promoting recovery from cognitive deficits and AD‐type pathology." (PMID 40236783, 2025). "Acetic acid has been shown to alleviate cognitive impairment in type 1 diabetic mice, and butyrate ameliorates cognitive deficits in AD mouse models via binding to its receptors FFAR2 and FFAR3." (PMID 40236783, 2025).
viral infection (3 papers, 2023 to 2025). "To test the impact of GPR41 and GPR43 on CD8+ T cell priming following viral infection, we infected C57BL/6 wildtype (WT) mice and mice lacking GPR41 and GPR43 (Ffar2–/–;Ffar3–/–) epicutaneously with HSV-1 and examined the endogenous HSV-specific CD8+ T cell response using H2-Kb-gB498-505 tetramers." (PMID 38524121, 2024).
Arrhythmia (2 papers, 2022 to 2024). Any cardiac rhythm other than the normal sinus rhythm. "We confirmed sodium acetate (C2) and sodium butyrate (C4) protect from C. sakazakii-induced arrhythmia, and C2 and C4 protected from septic arrhythmia by activating free fatty acid receptor 2 and 3 (FFAR2 and FFAR3) in mice." (PMID 39228788, 2024).
Glucose intolerance (2 papers, 2022 to 2025). Glucose intolerance (GI) can be defined as dysglycemia that comprises both prediabetes and diabetes. "Specifically, in our hands, in parallel to the increased body weight, FFAR3 ablation induced a marked glucose intolerance upon HFD feeding." (PMID 36362376, 2022). "More strikingly, the increased body weight and glucose intolerance developed by FFAR3 ablation under HFD feeding is completely abrogated in Tg-FFAR3−/− mice." (PMID 36362376, 2022). "While compelling evidence supports that FFAR3 ablation reduces insulin secretion and hence induces a marked glucose intolerance, others have found that FFAR3−/− mice exhibit improved glucose homeostasis." (PMID 36362376, 2022). "However, this may not be the only cause underlying this glucose intolerance, as FFAR3 is not exclusively expressed in intestinal cells." (PMID 36362376, 2022). "Thus, SCFAs protect obese mice from excessive body weight and glucose intolerance via mechanisms that are at least partly mediated by two out of the five FFA receptors (FFARs), namely FFAR2 and FFAR3." (PMID 36362376, 2022).
lung adenocarcinoma (2 papers, 2023 to 2024). A carcinoma that arises from the lung and is characterized by the presence of malignant glandular epithelial cells. "Although both FFAR2 and FFAR3 are receptors for SCFAs, only FFAR2 is highly expressed in tumor tissues and positively correlated with poor prognosis of lung adenocarcinoma patients." (PMID 38402237, 2024).
myocardial infarct (2 papers, 2022 to 2025). "The existence of FFAR2+ and FFAR3+ cells in human myocardial infarction tissue, by immunofluorescent co-staining for FFAR2/3 and canonical marker genes of monocytes and macrophages (CD14, CX3CR1, and CD68), indicating the existence of FFAR2/3 positive monocytes and macrophages." (PMID 40308581, 2025). "The proportion of FFAR2+ cells and FFAR3+ cells in normal heart hca dataset was much higher than that in the myocardial infarction datasets, which could be explained by the adoption of CD45+ cell enrichment method in hca dataset, leading to more captured myeloid cells." (PMID 40308581, 2025). "Despite the absence of FFAR3+ cells in the sma dataset, which may come from both low proportion and cell capture limitations, the existence of FFAR2+ and FFAR3+ monocytes and macrophages cells in human myocardial infarction tissue has been proved by immunofluorescent co-staining in this study." (PMID 40308581, 2025).
myocardial ischemia (2 papers, 2022 to 2025). A disorder of cardiac function caused by insufficient blood flow to the muscle tissue of the heart. "PA has been reported to interact with FFAR3 to protect against myocardial ischemia‐reperfusion injury via reducing oxidative stress." (PMID 40236783, 2025).
periodontitis (2 papers, 2023 to 2025). An acute or chronic inflammatory process that affects the tissues that surround and support the teeth. "Butyrate modulates periodontal mechanical nociception via FFAR3 signaling in P. gingivalis-induced periodontitis." (PMID 37893122, 2023). "In a study on a murine periodontitis model, butyrate was shown to modulate periodontal mechanical nociception through FFAR3 signaling, which may explain the often observed absence of pain in periodontitis." (PMID 37893122, 2023).
amyloid (1 paper, 2022). "Notably, a previous study addressing the role of FFAR3 in AD showed that Tg-FFAR3−/− mice showed a significant decrease in amyloid plaque burden." (PMID 36362376, 2022).
COVID-19 (1 paper, 2023). A disease caused by infection with severe acute respiratory syndrome coronavirus 2. "Cytokine production and signaling (including FFAR3 and IL27) was significantly increased in COVID-19, most markedly at T1 and T2." (PMID 37365222, 2023).
infarction (1 paper, 2025). A localised pathological necrosis of tissue resulting from obstruction of the blood supply usually by a thrombus, an embolus, or vascular torsion. "Our analysis highlights the FFAR2 and FFAR3 distribution in different cardiac tissue, cell types, and infarction areas, uncovering the potential effect and mechanisms of SCFAs via FFAR2 and FFAR3 in the heart, and provides a valuable reference for future studies." (PMID 40308581, 2025).
lung carcinoma (1 paper, 2023). "The clinical TCGA data showed a significant down-regulation of FFAR2, but not FFAR1, FFAR3, and FFAR4, in lung cancer, and a negative correlation with TLR2 and TLR3." (PMID 37287005, 2023).
multiple sclerosis (1 paper, 2024). A progressive autoimmune disorder affecting the central nervous system resulting in demyelination. "The interest in short-chain fatty acids (SCFAs) has grown steadily in recent years due to their clinical relevance in certain diseases such as multiple sclerosis and other inflammatory diseases, but not much is known of FFAR2 and FFAR3 (free fatty acid receptor 2 and 3) in pigs." (PMID 39024309, 2024).
neuroblastoma (1 paper, 2022). Neuroblastoma (NB) is the most common solid, extracranial childhood tumor. "Given that endogenous FFAR3 expression in Neuro-2A cells is equivocal (very low at best), we transfected these neuroblastoma cells to express human FFAR3, prior to their NGF-elicited neuronal differentiation." (PMID 35628613, 2022).
pheochromocytoma (1 paper, 2024). "In the present study, we examined the interplay of the sympatho-inhibitory α2A-AR and the sympatho-stimulatory FFAR3 in the regulation of CA secretion from rat adrenal chromaffin (pheochromocytoma) PC12 cells." (PMID 38791266, 2024).
renal fibrosis (1 paper, 2023). A final common manifestation of a wide variety of chronic kidney diseases characterized by glomerulosclerosis and tubulointerstitial fibrosis. "Our results highlight that KD attenuates UUO-induced renal fibrosis by enhancing FAO via the FFAR3-dependent pathway, which provides a promising dietary therapy for renal fibrosis." (PMID 37032786, 2023).
triple-negative breast carcinoma (1 paper, 2017). An invasive breast carcinoma which is negative for expression of estrogen receptor (ER), progesterone receptor (PR), and human epidermal growth factor receptor 2 (HER2). "Here, both FFAR2 and FFAR3 gene expression was significantly downregulated in invasive and triple negative breast cancer tissues when compared to normal breast tissues." (PMID 29049318, 2017).
metabolic disease (15 papers, 2014 to 2026). A congenital disorder (due to inherited enzyme abnormality) or acquired (due to failure of a metabolically important organ) disorder resulting from an abnormal metabolic process. "Due to the elevated expression of FFAR3 in endocrine tissues, including pancreatic islets and intestines, this receptor has been postulated as a key therapeutic target in metabolic diseases." (PMID 36362376, 2022).
cancer (14 papers, 2017 to 2024). A tumor composed of atypical neoplastic, often pleomorphic cells that invade other tissues. "In a similar manner to that described for FFAR2, the expression of FFAR3 was early detected in a human breast cancer line, and contradictory results have been reported about its expression in human cancer and its role in carcinogenesis." (PMID 33113952, 2020). "FFAR2 has been reported to have significantly reduced expression in colorectal adenocarcinoma, and propionate, the ligand for FFAR2 and FFAR3, is shown to reduce proliferation and promote apoptosis in several cancer cell types." (PMID 29049318, 2017). "Notably, the free fatty acid receptors FFAR1 (GPR40), FFAR2 (GPR43), FFAR3 (GPR41), and FFAR4 (GPR120) have the potential to bridge the genetic and environmental factors associated with cancer." (PMID 38243188, 2024). "Taken together these studies support a model by which reduced expression of FFAR2 and FFAR3 may contribute to cancer progression." (PMID 29049318, 2017). "Previous studies suggest that FFAR2 and FFAR3 are involved in the regulation of cancer development." (PMID 29049318, 2017). "These SCFA also act in downstream signaling pathways in CRC cells and in non-cancer cells including IEC and immune system cells through interaction with G protein coupled receptors (FFAR2/GPR43, FFAR3/GPR41, GPR109a, and Olfr78)." (PMID 31157230, 2019).
tumor (14 papers, 2018 to 2026). "FFAR2 and FFAR3 might participate in tumour suppression through propionate and butyrate, influencing cell proliferation and inducing apoptosis." (PMID 36765550, 2023). "It has been proposed that FFAR2 and FFAR3 might participate in tumour suppression through propionate and butyrate, influencing cell proliferation and inducing apoptosis." (PMID 33716996, 2021). "Recent works suggested that FFAR2 and FFAR3 played a role in tumor suppression." (PMID 32806665, 2020). "However, these conclusions should be taken carefully, because this organoid model experimental study does not consider variables such as host and tumour microenvironment, namely on the bioavailability of SCFAs and the expression of FFAR2 and FFAR3." (PMID 33716996, 2021).
infection (12 papers, 2018 to 2025). The state of being infected such as from the introduction of a foreign agent such as serum, vaccine, antigenic substance or organism. "In line with this, gB498-505-specific CD8+ T cells were lodged into the skin of WT and Ffar2–/–;Ffar3–/– mice by day 9 post-infection." (PMID 38524121, 2024).
adenocarcinoma (1 paper, 2016). A common cancer characterized by the presence of malignant glandular cells. "The function of human and mouse FFAR2 and FFAR3 was also investigated via heterologous expression in human adenocarcinoma lung alveolar basal epithelial cell line, A549 (which has low endogenous levels of FFAR2 and FFAR3 [data not shown])." (PMID 27667443, 2016).
heart disease (1 paper, 2022). "For example, despite the mystery surrounding the underlying mechanism, vascular FFAR3 appears to promote vasodilatation, a therapeutically desirable effect in heart disease patients." (PMID 35328722, 2022).
movement disorder (1 paper, 2021). Neurological conditions resulting in abnormal voluntary or involuntary movement, which may impact the speed, fluency, quality and ease of movement. "Interestingly, a synthetic FFAR3 (GPR41) agonist (AR420626) corrected the movement disorder and neuronal loss in a 6-hydroxydopamine (OHDA, a neurotoxin)-induced PD mouse model." (PMID 34857900, 2021).
FFAR3 also shares sentences with these, for which no sentence is quoted: cardiovascular disease (7 papers); Hepatic steatosis (7); atherosclerosis (5); depression (4); inflammation (4); allergic asthma (3); cognitive decline (3); colon cancer (3); ulcerative colitis (3); Anxiety (2); Arthritis (2); Autoimmunity (2); chronic heart failure (2); coronary artery disease (2); endothelial dysfunction (2); Impaired glucose tolerance (2); liver cancer (2); metabolic syndrome (2); non-alcoholic fatty liver disease (2); Parkinson disease (2); steatosis (2); airway allergy (1); alcoholic liver diseases (1); allergies (1); atrial fibrillation (1); cardiac hypertrophy (1); Chronic colitis (1); colorectal adenoma (1); Constipation (1); Crohn disease (1).
A further 28 diseases each share a sentence with FFAR3 in 1 paper.